G6PD (glucose-6-phosphate dehydrogenase)
Diseases named in the same sentence as G6PD in open-access papers (continued):
Sharing a sentence is not in itself a finding about the gene and the disease.
COVID-19 (continued). "Therefore, G6PD deficiency and the NADPH–ROS axis orchestrate a multifaceted pathophysiological response in general, which becomes extremely fatal during COVID-19." (PMID 35880537, 2022). "Given recent studies on SCD and risk of severe COVID-19 outcomes, we evaluated whether the copresence of SCD and G6PD would affect the outcome by looking at presence of effect measure modification of SCD on the G6PDd and the primary outcome." (PMID 34584152, 2021). "Therefore, in COVID-19 patients, inadequate G6PD activity should be considered and can be monitored with biomarkers." (PMID 33195336, 2020). "One possible explanation for the last observation is that G6PD-deficient individuals above 80 years of age may have a higher risk of mortality from COVID-19 and, therefore, may not have been included in the study sample." (PMID 37376524, 2023). "Therefore, the activity of G6PD may be increased in COVID-19 patients raising the level of the NADPH, which is needed for the enzymatic and non-enzymatic antioxidant systems that counteract the oxidative stress caused by the cytokine storm." (PMID 35805067, 2022). "In our study, comparing the COVID-19 positive G6PD deficient group with COVID-19 negative G6PD deficient group showed that COVID-19 infection increased significantly the total WBC, lymphocytes count, and ANC but did not increase bilirubin level or decreased Hb level or hematocrit (no hemolysis)." (PMID 36466438, 2022). "We suggest that variations in the G6PD gene could significantly affect risk of adverse effects of CQ/HCQ, and recommend that this should be evaluated in clinical trials of CQ/HCQ treatment for COVID-19." (PMID 34302047, 2021). "However, preliminary studies did not confirm an association between COVID-19 and this deficit or differences between asymptomatic and symptomatic infected patients, even if a G6PD deficit was present in more than 30% of infected subjects." (PMID 33669011, 2021). "Seven (53·8%) patients received tafenoquine, and causes of death were electric shock, cancer, COVID-19, hypertension, external cause (injury), and two with undetermined cause: one died at 329 days after treatment (G6PD status unknown) and one at 40 days after treatment (G6PD normal)." (PMID 38365417, 2024). "An increase in the activity of G6PD raises NADPH, which is used by the enzymatic and non-enzymatic antioxidant systems to counteract the OS caused by the cytokine storm in COVID-19 patients." (PMID 35805067, 2022). "As per univariate and multivariate prognostic analyses, a few important genes, including ALPL, ANGPT2, CD4, G6PD, SERPINE1 and TNNI3, may serve as independent prognostic factors for HCC patients with COVID-19." (PMID 36275701, 2022). "In addition, the large cohort of group of COVID-19 patients without G6PD condition will provide valuable support to the findings of the study groups." (PMID 37376524, 2023).
Hyperglycemia (35 papers, 2011 to 2025). An increased concentration of glucose in the blood. "Avoid perioperative hypothermia, acidosis, hyperglycemia and postoperative infection can precipitate haemolysis in the G6PD-deficient patient." (PMID 40227005, 2025). "Other research suggests that hyperglycemia-induced G6PD ubiquitination is the main cause of podocyte injury and loss, which eventually leads to an increase in urinary albuminuria." (PMID 39140974, 2024). "In Trinidad, the management of two imported cerebral malaria cases was complicated by their G6PD-deficient status, with the occurrence of blackwater fever, cerebral manifestations, renal impairment, hyperglycaemia and thrombocytopaenia." (PMID 24568147, 2014). "Hyperglycemia inhibits G6PD activity leading to gradual loss of β-cells." (PMID 34371645, 2021). "Moreover, the overproduction of superoxide caused by hyperglycemia inhibits glucose-6-phosphate dehydrogenase that is the rate-limiting enzyme of the pentose phosphate pathway able to provide reducing equivalents to the endogenous antioxidant defense system." (PMID 32630636, 2020). "While our genetic findings could not determine whether this difference was completely attributable to relative hyperglycemia, accounting for the effect of the G6PD variant that lowers HbA1c only in African Americans would further widen this disparity." (PMID 28898252, 2017). "Increased expression of G6PD in response to tRES+HESP in HAECs is implicated in correction glycolytic overload and cell dysfunction in hyperglycemia." (PMID 40867852, 2025). "It has been shown that hyperglycemia induces G6PD activity and expression profiling in different tissues in animal models in the early stages of the disease." (PMID 39519313, 2024). "In an earlier study, decreased G6PD activity that was altered by hyperglycemia was restored by spironolactone, a MR blocker." (PMID 34285713, 2021). "In hyperglycemia and obesity, the G6PD expression is increased, leading to the development of insulin resistance." (PMID 33490239, 2020). "In support of the current data, studies of rat liver and pancreas indicate that hyperglycaemia results in reduced G6PD activity, with this accompanied by a reduced NADPH/NADP+ ratio, and decreased GSH levels." (PMID 24466151, 2014). "Both posttranslational mechanisms and decreased gene expression appear to be involved in the decrease of G6PD activity that was observed after exposure to high levels of hyperglycemia (20–30 mmol/L)." (PMID 26317017, 2013). "In STZ-induced diabetic murine model, G6PD activity in liver reduces significantly which obstructs glucose utilization and leads to hyperglycemia." (PMID 19389871, 2011). "Therefore, our results provide important clinical support for the inhibitory effect of hyperglycemia on G6PD activity." (PMID 39140974, 2024). "Moreover, animal studies indicate a bi-directional link between hyperglycemia and the overexpression of glucose-6-phosphate dehydrogenase (G6PD), the first and rate limiting enzyme in PPP observed in adipocytes and hepatocytes." (PMID 36615861, 2023). "Importantly, glucose-6-phosphate dehydrogenase expression and activity are decreased by hyperglycemia, with a reduction in GSH reductase activity, rendering pancreatic β-cells susceptible to oxidative damage via the GSH/GSSH ratio." (PMID 36430158, 2022). "Polysaccharides inhibited hyperglycaemia by regulating the expression of several key enzymes in the glucose metabolism pathway, such as hepatic glucokinase, phosphofructokinase, G6PD, hepatic glycogen phosphorylase, fructose-1,6-bisphosphatase, phosphoenolpyruvate carboxykinase, and G6Pase." (PMID 34026300, 2020). "Insulin resistance causes severe hyperglycemia and does not detect the available glucose; instead, it causes the collective action of increasing the secretion of glucose-6-phosphate dehydrogenase, hexokinase, and glucokinase." (PMID 30937278, 2019). "Hyperglycemia decreases G6PD activity, supported by experimental observations." (PMID 26317017, 2013).
Hyperglycemia (continued). "Our data show that hyperglycaemia during HFD can reduce G6PD activity." (PMID 21235803, 2011). "This decrease could be explained by hyperglycemia associated with the HFD, which caused the activation of protein kinase A and a subsequent increase in the phosphorylation and inhibition of G6PD activity and thereby a decrease in NADPH levels, leading to increased oxidative stress." (PMID 26228038, 2015). "In an animal study inducing mild, moderate, and severe hyperglycemia through STZ and nicotinamide treatment, it was observed that hepatocyte G6PD activity levels in mild hyperglycemia remained comparable to normal values." (PMID 40603345, 2025). "Hyperglycemia and subsequent oxidative stress in DKA can impair the function of the G6PD enzyme, leading to the increased vulnerability of red blood cells (RBCs) to oxidative damage and subsequent hemolysis." (PMID 38966448, 2024). "To functionally evaluate the role of the PPP we inhibited glucose-6-phosphate dehydrogenase, the enzyme involved in the first step of the pathway generating one NADPH, using 6-AN to see if the suppression by hyperglycemia on glucose oxidation was abolished." (PMID 31540443, 2019). "An in vivo study also demonstrated significance increase of G6PD expression and activity, NADPH levels, and 6-phosphogluconic acid generation in the liver of adult male Zucker fa/fa rats, a prototype model of hyperglycemia and type 2 diabetes." (PMID 28424674, 2017). "Moreover, our genetically modified mice never showed any signs of hyperglycemia as determined by hexokinase/glucose-6-phosphate dehydrogenase (Roche)." (PMID 25126760, 2014).
colon carcinoma (32 papers, 2010 to 2025). "Previous work in colon cancer cells reported that G6PD deletion caused defects in folate-dependent biosynthesis." (PMID 39365851, 2024). "A new study revealed that the activity and expression of G6PD are enhanced in colon cancer (CC) cells and that increased G6PD expression is associated with aggressive CC behavior." (PMID 38184562, 2024). "Then, we wanted to explore the mechanism underlying the increase of G6PD expression after glutamine deprivation in colon cancer cells." (PMID 34572981, 2021). "We also demonstrate that increased G6PD expression was associated with aggressive colon cancer behavior." (PMID 28542136, 2017). "Data concerning mutations in HPRT and G6PD genes, analyzed here in two different colon tumours and nearby normal intestinal tissues of two male patients, lend support to this hypothesis." (PMID 20186333, 2010). "On the other hand, the G6PD was used to explain BPA-mediated diseases in colon cancer cells (SW480), mammary glands, and Sertoli cells because the G6PD was accepted as one of the sensitive biomarkers and can be used for the prediction of BPA-mediated diseases." (PMID 36992836, 2023). "In HCT116 colon cancer cells, G6PD knockdown reduces the NADPH/NADP+ ratio and oxidative stress sensitivity and inhibits growth." (PMID 36662190, 2022). "Another study on colon cancer found that LINC00242 and G6PD were significantly overexpressed in colon cancer." (PMID 36185280, 2022). "A recent study showed that butyrate can down-regulate the G6PD mRNA and protein levels, reduce the DNA synthesis activity and further enhance the apoptosis efficacy of 5-FU on colon cancer cells." (PMID 35207558, 2022). "Considering this, we examined the role of the G6PD enzyme in the proliferation of colon cancer cell models." (PMID 34572981, 2021). "We demonstrated that both G6PD inhibition and glutamine deprivation led colon cancer cells into cell cycle arrest and subsequent decrease in proliferation." (PMID 34572981, 2021). "G6PD upregulation has been proposed as an indicator of poor prognosis in several types of cancers, including colon cancer." (PMID 34572981, 2021). "In this study, we manifestly showed the importance of the PPP enzyme G6PD and glutamine for the proliferation and survival of colon cancer cells." (PMID 34572981, 2021). "Next, we wanted to better explore the mechanism through which G6PD inhibition and glutamine deprivation reduced colon cancer cell proliferation." (PMID 34572981, 2021). "Accordingly, we selected HT29 and HCT116 cell lines to further characterize the function of G6PD in colon cancer." (PMID 34572981, 2021). "We showed that G6PD is overexpressed in colon cancer cells upon glutamine withdrawal following an increase in ROS and NRF2 protein levels." (PMID 34572981, 2021). "In this study, we demonstrated that both inhibition of G6PD and glutamine deprivation decrease the proliferation of colon cancer cells and induce cell cycle arrest and apoptosis." (PMID 34572981, 2021). "In the current study, we systematically demonstrated that piRNA‐823 regulates the proliferation, invasion and apoptosis of colon cancer cells by piRNA‐823/G6PD/HIF‐α pathway." (PMID 32596991, 2020). "The previous studies show that G6PD is involved in RCC proliferation and associated with survival, and is a drug resistance gene in colon cancer." (PMID 30603059, 2018). "Using a histochemical technique, an increased G6PD activity was reported in human cervical cancer and colon carcinoma." (PMID 28553614, 2017). "The results showed that PAK4 expression was positively correlated with G6PD expression (P=0.041) in colon cancer tissues." (PMID 28542136, 2017).
colon carcinoma (continued). "PAK4 and G6PD were highly expressed in 50% (13/26) and 61.5% (16/26) of colon cancer samples, respectively." (PMID 28542136, 2017). "Taken together, these results suggested that PAK4 promoted glucose consumption and NADPH production in colon cancer cells via increasing the enzyme activity of G6PD." (PMID 28542136, 2017). "We also performed immunohistochemical staining of PAK4 and G6PD in 154 cases with colon cancer to confirm this observation." (PMID 28542136, 2017). "The results were consistent with our findings that PAK4 upregulated G6PD activity in colon cancer cell lines." (PMID 28542136, 2017). "The results presented here provide evidence of a similar value of genetic heterogeneity in HPRT and G6PD transcripts in cells of colon carcinoma and nearby healthy tissues in the two studied patients." (PMID 20186333, 2010). "The results show that genetic heterogeneity is detectable in HPRT and G6PD transcripts in both tumors and nearby healthy tissues of the two studied colon tumors." (PMID 20186333, 2010). "However, similar to the tissues with an active metabolism such as liver, adipose, or mammary glands, tumor cells, including colon cancer cells, are reported to have high levels of G6PD due to their higher consumption of NADPH compared to quiescent cells." (PMID 34572981, 2021). "Our results showed that IC261 could decrease the protein expression of TIGAR and increase the protein expression of G6PD in colon cancer cells." (PMID 32071557, 2020). "Together, these data indicated that G6PD was a PAK4-binding protein in colon cancer cells." (PMID 28542136, 2017). "Notably, we showed that there was a strong positive correlation between PAK4 and G6PD expression in colon cancer specimens and that the expression of PAK4 or G6PD was positively correlated with an aggressive phenotype of clinical colon cancer." (PMID 28542136, 2017). "In addition, we demonstrated a close positive correlation between PAK4 and G6PD expression in colon cancer specimens." (PMID 28542136, 2017). "Importantly, for the first time, we established a correlation between PAK4 and G6PD in colon cancer with clinicopathological analysis." (PMID 28542136, 2017). "Furthermore, expression of PAK4 or G6PD was positively correlated with an aggressive phenotype of clinical colon cancer." (PMID 28542136, 2017). "Therefore, inhibition of PAK4 and/or G6PD activity might be a potential therapeutic strategy for colon cancer." (PMID 28542136, 2017). "POU2F1 over-expression significantly increased glucose consumption, lactate production levels and glucose-6-phosphate-dehydrogenase (G6PD) activity, whereas POU2F1 silencing had opposite effects on colon cancer cells (p < 0.01)." (PMID 34997215, 2022). "In another research work, DOX-resistant human colon cancer cells that displayed increased activity of PPP and G6PD have lower intracellular DOX accumulation in comparison with DOX-sensitive counterpart." (PMID 35173543, 2022). "This crosstalk between G6PD and glutamine points out the potential of combined therapies targeting oxidative PPP enzymes and glutamine catabolism to combat colon cancer." (PMID 34572981, 2021). "In this study, we investigated the effect of G6PD inhibition and the link between glutamine metabolism and PPP in colon cancer cells, taking into account the high reliance of these types of cancer cells on PPP." (PMID 34572981, 2021). "Here, we first showed that G6PD has an important role in the proliferation of HT29 and HCT116 colon cancer cells." (PMID 34572981, 2021). "In our study, eight proteins including G6PD, GPX3, and LAP3 which are reported to be involved in colon cancer cell growth were connected to glutathione metabolism." (PMID 34386520, 2021).
colon carcinoma (continued). "We found that POU2F1 transcripts were positively correlated with hexokinase 2 (HK2), 6-phosphofructo-2-kinase/fructose-2,6-biphosphatase 2 (PFKFB2), ALDOA, pyruvate kinase M1/2 (PKM), lactate dehydrogenase A (LDHA), G6PD, and ribose 5-phosphate isomerase A (RPIA) levels in the colon cancer tissues." (PMID 34997215, 2022). "To test the reliance of colon cancer cells on the oxidative phase of PPP for proliferation and other cellular functions, we inhibited G6PD using a pool of small interference RNA (siRNA) containing four different sequences targeting different exonic regions of the G6PD gene (siG6PD)." (PMID 34572981, 2021). "We first measured the specific enzyme activity of G6PD in a panel of colon cancer cells and observed that it was highly upregulated in colon cancer cells compared to non-tumor NCM460 colon cells." (PMID 34572981, 2021). "Moreover, resveratrol (RSV, 3,5,4′-trihydroxy-trans-stilbene), a phytoalexin found in the skin of red grapes and peanuts, suppressed cell cycle progression in HT29 advanced human colon cancer cells by downregulating two key enzymes of the PPP, G6PD, and TKT." (PMID 28553614, 2017). "G6PD and TKT enzymatic activities have been reported to be enhanced during late G1 and S cell cycle phases and specific upregulation of the oxidative branch has been demonstrated in colon cancer cells." (PMID 29290982, 2017). "In the present study, we identified elevated expression levels of G6PD in colon cancer tissues compared with noncancerous tissues in 100 out of 154 colon cancer patients." (PMID 28542136, 2017). "In their studies, single and combinational knockouts of G6PD, malic enzyme 1, and isocitrate dehydrogenase 1 identify the PPP as the largest contributor to NADPH production, indicating these other enzymes function as “backups” in colon cancer, with little impact on NADPH production." (PMID 40802750, 2025). "In colon cancer, the destroyed NADPH dynamic balance mediated by G6PD could enhance oxaliplatin-induced apoptosis of colon cancer cells through REDOX regulation; thus, G6PD could be a potential prognostic biomarker and a promising target for colon cancer treatment." (PMID 32903581, 2020). "The levels of G6PD and PAK4 were increased in colon cancer tissue samples compared with adjacent noncancerous tissue samples." (PMID 28542136, 2017). "Unlike noncancerous tissues, high expression levels of G6PD and PAK4 were observed in colon cancer tissues (right)." (PMID 28542136, 2017).